EGFR (epidermal growth factor receptor)
Diseases named in the same sentence as EGFR in open-access papers (continued):
Sharing a sentence is not in itself a finding about the gene and the disease.
oesophageal cancer (continued). "This allowed the therapy independent prognostic impact of EGFR FISH status to be examined in the population of advanced oesophageal cancers that have been, and most likely will be, evaluated in future clinical trials of anti-EGFR agents." (PMID 26478746, 2015). "Clinical trials of agents targeting epidermal growth factor receptor (EGFR) in esophageal carcinoma (EC) have indicated a minority subgroup responsive to anti-EGFR therapies." (PMID 26478746, 2015). "A previous evaluation of multiple studies with more than 20,000 patients also showed that high EGFR expression is associated with lower RFS for patients with head and neck, ovarian, cervical, bladder and oesophageal cancers." (PMID 24354805, 2013). "Monoclonal antibodies targeting EGFR are being extensively evaluated in several cancer types including oesophageal cancer." (PMID 21245865, 2011). "Epidermal growth factor receptor is often abundantly expressed in oesophageal cancer and therefore we tested the ability of gefitinib to inhibit cell proliferation." (PMID 19142186, 2009). "Epidermal growth factor receptor is often overexpressed in patients with oesophageal cancer, suggesting an important role for it in the development of this disease." (PMID 19142186, 2009). "Above all, prospective works assessing EGFR diffuse expression and its relationship to clinical response to EGFR-targeted therapies are definitely needed in oesophageal cancer." (PMID 15986037, 2005). "Furthermore, DEX inhibits the growth and metastasis of esophageal carcinoma cells through upregulating miR-143-3p and reducing epidermal growth factor receptor." (PMID 41409241, 2025). "It will be important to assess the impact of inhibitors of the PI3K-AKT-mTOR pathway in the near future to determine to what extent this pathway could be more efficient than the EGFR pathway for oesophageal cancer growth and progression." (PMID 35326673, 2022). "Targeting EGFR with EGFR tyrosine kinase inhibitors (TKi), such as gefitinib, erlotinib or afatinib, inhibits the proliferation of oesophageal cancer cell lines in vitro, but, clinical trials of EGFR inhibitors in oesophageal cancer, including ESCC, have shown mixed results." (PMID 33169187, 2021). "Thus, targeting the YAP‐EGFR axis may be more efficacious than targeting EGFR alone as a treatment of oesophageal cancer." (PMID 32281270, 2020). "This correlates with the current therapeutic focus on EGFR which includes clinical trials for advanced EC with high HER-2 expression, showing the therapeutic potential of EGFR targets in oesophageal cancer." (PMID 35281814, 2022). "As a result, the combination of adagrasib (MRTX849) with EGFR or ERBB inhibitors was significantly better than single agents in xenograft models of KRASG12C-mutant H2122 (NSCLC) and KYSE-410 (esophageal carcinoma)." (PMID 36483040, 2022). "In spite of the frequency of the molecular alterations of PI3K in oesophageal cancer, the PI3K-AKT-mTOR pathway has received less attention than EGFR or VEGF in ESCC and EAC." (PMID 35326673, 2022). "Expression analysis of miR-196a-5p and miR-1-3p targets in TCGA using the UALCAN tool showed that CCND1, CASP3, EGFR, and CDC42 were overexpressed in esophageal carcinoma, compared to normal esophagus samples." (PMID 32412911, 2020). "Results indicated that the expression of four target genes (CCND1, CASP3, EGFR, and CDC42) was markedly upregulated in esophageal carcinoma." (PMID 32412911, 2020). "Subsequent to SCOPE-1, several other studies have reported outcomes from EGFR inhibition and CRT in oesophageal cancer." (PMID 28196063, 2017).
oesophageal cancer (continued). "In addition to anti-EGFR monoclonal antibodies, orally active tyrosine kinase inhibitors (TKIs), small molecules that block the binding site of the EGFR tyrosine kinase, have been evaluated in patients with chemotherapy refractory advanced gastric and oesophageal cancer." (PMID 27514667, 2016). "As is known, overexpression of EGFR and HER2 has been observed in over 30% of esophageal carcinomas, and their overexpression is correlated with reduced survival, increased risk of recurrence, distant metastasis, and resistance to radiotherapy." (PMID 24664246, 2014). "Similarly, in the xenograft models of the NSCLC cell line H2122 and esophageal carcinoma cell line KYSE-410, adagrasib, in combination with other EGFR inhibitors, such as afatinib, resulted in a desirable outcome." (PMID 35053550, 2022). "Anti-epidermal growth factor receptor (EGFR) therapy has been widely used in the treatment of malignancies, and chemotherapy regimens that include nimotuzumab have been confirmed to have satisfactory efficacy among esophageal carcinoma (EC) patients." (PMID 33194681, 2020). "Actually, the coexpression of Grb7 with EGFR was significantly related to advanced esophageal carcinomas with extramucosal invasion, whereas this phenomenon was not induced by the sole expression of Grb7 or EGFR." (PMID 31083325, 2019). "Therefore, the effects of some monospecific antibodies and tyrosine kinase inhibitors that block EGFR or HER2 function, such as cetuximab, trastuzumab, gefitinib, and erlotinib on esophageal carcinoma have been examined, but the efficacy is limited so far." (PMID 24664246, 2014).
diabetic nephropathy (54 papers, 2009 to 2025). "The EGFR gene is a cellular growth pathway regulator implicated in diabetic nephropathy while IGF1R can activate cascades of intracellular proteins involved in glucose and lipid metabolism." (PMID 41031259, 2025). "The EGFR inhibitor erlotinib was associated with a reduction in albuminuria and glomerular injury in diabetic nephropathy and an increase in autophagy in the kidney." (PMID 36993805, 2023). "For instance, EGFR activation had a significant role in activating pathways that mediate podocyte injury and loss in diabetic nephropathy." (PMID 33968154, 2021). "This is evident by the observations that EGFR inhibition led to less podocyte loss in models of diabetic nephropathy while podocyte-specific deletion of EGFR attenuated albuminuria and podocyte loss induced by hyperglycemia." (PMID 33574751, 2020). "Furthermore, abnormal EGFR activation has been implicated in mediating progressive kidney injury, particularly in diabetic kidney disease." (PMID 40141782, 2025). "Furthermore, the EGFR is activated/transactivated by multiple factors inherent in the diabetic milieu, including high glucose, angiotensin II (AngII), and aldosterone, all of which have been implicated in the pathogenesis of diabetic nephropathy." (PMID 23533381, 2013). "Hence we hypothesise that the EGFR plays a role in the development of diabetic nephropathy as well as in the associated sodium and water retention, which is exacerbated by concomitant treatment with PPARγ agonists." (PMID 23533381, 2013). "Regarding kidney disease, Josephine M’s team discovered a correlation between epidermal growth factor receptor (EGFR) and diabetic kidney disease (DKD) risks across all models." (PMID 40661817, 2025). "The increase in ER stress, ROS level and EGFR protein observed in the diabetic nephropathy has suggested a possible link between these signalling pathways." (PMID 39966897, 2025). "Contrary to our results, EGFR inhibitor ameliorates the progression of diabetic nephropathy and enhances pancreatic insulin production, resulting in preserved β-cell function and reduced systemic oxidative stress." (PMID 41189666, 2025). "The evidence of the relationship between APN overexpression and EGFR inhibition prompted investigation into the potential impact of APN-mRNA-LNP injections on other pathological conditions related to diabetic nephropathy." (PMID 38916734, 2024). "EGFR activation is linked to damage and loss of podocytes, specialized cells critical for kidney function, while the deletion of EGFR in podocytes mitigates glomerular injury and offers protection against kidney damage in the context of diabetic nephropathy." (PMID 38766523, 2024). "The epidermal growth factor receptor inhibitor erlotinib slowed the progression of STZ-induced diabetic nephropathy in mice, including reduced albuminuria and histological injury." (PMID 38778209, 2024). "There is increasing evidence that aberrant EGFR activation is a mediator of progressive kidney injury in diabetic kidney disease." (PMID 36359813, 2022). "Previous studies had indicated that renal epidermal growth factor receptors (EGFRs) were activated in models of diabetic nephropathy (DN), and inhibition of EGFR activity protected against progressive DN in T1 DM and T2 DM." (PMID 33204295, 2020). "In conclusion, we demonstrated that EGFR plays a pivot role in diabetic nephropathy pathogenesis via up-regulating ROS generation and ER stress." (PMID 28427241, 2017). "For example, a recent study in a model of type 1 diabetes showed that up to 24 weeks of treatment with the EGFR inhibitor, Erlinotib, attenuated progression of diabetic nephropathy." (PMID 26167903, 2015). "EGFR is upregulated in various forms of renal disease including diabetic nephropathy, glomerulonephritis, and allograft nephropathy." (PMID 23533381, 2013).
diabetic nephropathy (continued). "A careful modular dissection and examination of networks from diabetic nephropathy datasets exhibit the interactions between EGFR with PTPN1 and CAV1 through AKT1 activation." (PMID 19997558, 2009). "At the same time, a relation between EGFR and ROS levels has been observed in the progression of diabetic nephropathy, a kidney disease due to abnormality and microvascular complications in diabetic patients that leads to the dysregulation of many homeostatic signalling pathways." (PMID 39966897, 2025). "In addition, they reported that EGFR expression is reduced in renal tissue of rats with diabetic nephropathy and high glucose-induced podocytes." (PMID 40713496, 2025). "Aberrant EGFR activation is a mediator of progressive kidney injury in diabetic nephropathy." (PMID 40391375, 2025). "PAK6 and EGFR, which are significantly more abundant in the uEVs of patients with diabetic nephropathy than in those of healthy controls and patients with T2DM, may be biomarkers for diagnosing diabetic nephropathy." (PMID 40873806, 2025). "Summary of selected studies highlighting the role of EGFR signalling in diabetic nephropathy." (PMID 39234105, 2024). "This induction was associated with several positive outcomes, such as preventing diet-induced body weight gain, improving hyperglycemia by promoting Glut-4 expression, alleviating diabetic nephropathy symptoms by blocking the EGFR pathway, and reducing pro-inflammatory cytokine production." (PMID 38916734, 2024). "The results showed that Schisandrin A had a protective effect on diabetic nephropathy, EGFR might be a potential therapeutic target, and AKT/GSK-3β might be involved in this process." (PMID 39194535, 2024). "In addition, deletion of EGFR in podocytes also leads to delaying the development of diabetic nephropathy." (PMID 36532549, 2022). "Notably, upregulation of Rubicon was epidermal growth factor receptor (EGFR) signaling-dependent, and deletion of EGFR in glomerular podocytes ameliorated diabetic kidney disease via Rubicon suppression-dependent autophagic activation." (PMID 35083223, 2021). "Recently, it has been found that targeting EGFR might also hold a therapeutic potential for Diabetic kidney disease." (PMID 34535145, 2021). "In addition to being directly related to T2DM, the polymorphisms of VEGFA, EGFR, PTGS2, and AKT1 genes are mainly related to diabetic vascular dysfunction and play an important role in diabetic vascular disease and diabetic nephropathy." (PMID 33134394, 2020). "It is possible that the activation of EGFR in diabetic kidney disease may mediate EMT, thus promoting interstitial fibrosis." (PMID 33574751, 2020). "Recent studies have supported the hypothesis that inhibition of the EGFR provides an attractive therapeutic target for the treatment of diabetic nephropathy." (PMID 23533381, 2013). "On the other hand, decreased miR-192 was noted in biopsy specimens of patients with advanced diabetic nephropathy, while miR-192 expression was positively correlated with EGFR and negatively correlated with the degree of fibrosis suggesting a protective role for miR-192." (PMID 23358711, 2013). "Interestingly, this study showed that ADAM17 upregulation in conditions of hyperglycemia might be self-augmented via an EGFR/ADAM17 signaling loop and further implicated ADAM17 as a target in treating diabetic kidney disease." (PMID 39234105, 2024). "Thus, we think that treating diabetic nephropathy may be affected by controlling PTRF expression by blocking the EGFR tyrosine kinase." (PMID 39194535, 2024). "Although EGFR blocking antibodies and tyrosine kinase inhibitors are widely used in cancer therapy, there are serious concerns about whether they could ever be employed as therapeutic agents in kidney diseases, and specifically in diabetic nephropathy." (PMID 36359813, 2022).
diabetic nephropathy (continued). "Furthermore, some studies reported that the EGFR blockade may also indirectly protect against diabetic nephropathy by increasing islet prosurvival autophagy activity." (PMID 32695255, 2020). "Therefore, we investigated whether oxidative stress and ER stress were involved in the attenuation of diabetic nephropathy after EGFR inhibition." (PMID 28427241, 2017). "Thus blocking EGFR/AKT/ROS/ER stress pathway may serve as a potential therapeutic strategy in preventing diabetic nephropathy." (PMID 28427241, 2017). "Hence targeting the EGFR in combination with the PPARγ agonist has the potential to be beneficial in regulating nephromegaly, matrix expansion, and fibrosis in addition to excessive sodium reabsorption observed in diabetic nephropathy." (PMID 23533381, 2013). "Transactivation of the epidermal growth factor receptor in mesangial cells and HB-EGF contributes to glomerular matrix accumulation, leading to diabetic kidney disease." (PMID 40698658, 2025). "Other studies have shown that blocking the activation of epidermal growth factor receptor (EGFR) can inhibit the infiltration and oxidative stress of kidney immune cells, increase islet autophagy activity, and improve diabetic nephropathy." (PMID 33603663, 2020). "On the basis of these observations supported by the literature, we have proposed the interactions of PTPN1 with EGFR and with CAV1 as the new potential interactions in diabetic nephropathy." (PMID 19997558, 2009). "In podocytes of diabetic nephropathy, downregulated Gprc5a mediates podocyte foot process effacement, FSGS, and proteinuria by upregulating EGFR and TGF-β signaling pathways; an upregulated EGFR signal can also promote the activation of the TGF-β signaling pathway." (PMID 33921219, 2021). "However, inhibition of EGFR showed therapeutic potential for AKI during endotoxemia and diabetic nephropathy." (PMID 32695255, 2020). "Inhibition of EGFR attenuates damage of DN through EGFR/AKT/ROS/ER stress signaling, which could be a potential therapeutic target in diabetic kidney diseases." (PMID 28427241, 2017). "(c) The third network portrays unique interactions PTPN1 with EGFR and CAV1 which could lead to an impaired vascular function in diabetic nephropathy condition." (PMID 19997558, 2009). "Researchers have determined that phospholipase Cr1 interacts with activated EGFR and transactivates through PI3K-PKCβ1-AKT signaling in mesangial cells to mediate hyperglycemia-induced up-regulation of type I collagen, thereby affecting the development of diabetic nephropathy." (PMID 37996895, 2023).
ovarian tumors (53 papers, 1992 to 2025). "Activation of the EGFR in ovarian tumors is associated with increased malignancy and poor patient outcome." (PMID 26351843, 2015). "A study by Teplinsky and Muggia also found high expression of EGFR in women with ovarian tumors, which may be associated with tumor progression." (PMID 35807169, 2022). "One possible explanation is that despite possessing highly elevated levels of EGFR protein, ovarian tumors present only rarely with EGFR mutations, while response to EGFR TKIs in other tumor types such as non-small cell lung cancer (NSCLC) is highly dependent on the presence of mutated EGFR." (PMID 28740577, 2017). "Over-expression of EGFR or its mutations are reported in approximately 70% of ovarian tumors." (PMID 22952709, 2012). "A recent study has shown that intraperitoneal injections of anti‐human epidermal growth factor receptor (EGFR) antibody‐modified LNPs achieved up to 80% gene editing in ovarian tumor mouse models, leading to suppressed tumor growth and extended survival rates." (PMID 40014809, 2025). "EGFR-targeted NIR-PIT was tested in ovarian tumor cluster spheroids grown either under flow or static conditions and was found to be equally effective in both settings." (PMID 35158887, 2022). "FGFR or EGFR expression was initially assessed in a series of ovarian tumor and normal tissues based on GEO dataset." (PMID 33604191, 2021). "The current study shows, for the first time, the impact of flow-induced shear stress on resistance to carboplatin and modulation of EGFR-mediated survival pathways in adherent 3D ovarian tumors." (PMID 32231055, 2020). "Based on their high background staining in tumor-negative tissues and heterogenous expression patterns in primary ovarian tumors, EGFR, VEGF-A and L1CAM were excluded from further analyses." (PMID 32545676, 2020). "Gefitinib is a tyrosine kinase inhibitor that targets the epidermal growth factor receptor (EGFR), which is overexpressed in lung, colon, breast, brain, and ovarian tumors." (PMID 31547272, 2019). "The results of our study show the presence of nuclear localization of EGFR in ovarian tumours particularly in BOTs and LGSCs." (PMID 26870997, 2016). "In fact, the epidermal growth factor receptor (EGFR) is expressed in 70% of ovarian tumors and agents that target this receptor have shown antitumor activity in preclinical models." (PMID 26336133, 2015). "Binding of PEA3 to the MT1-MMP promoter in ovarian tumor cells is mediated through epidermal growth factor receptor (EGFR) signaling pathway." (PMID 23967226, 2013). "A study conducted by Alper and colleagues have shown that approximately 70% of ovarian tumors express high levels of EGFR." (PMID 22952709, 2012). "Our results showed that PEITC inhibits ovarian tumor growth in vivo by suppressing EGFR-AKT pathway and identifies EGFR-Akt axis as a target of PEITC." (PMID 22952709, 2012). "The overexpression of growth factor receptors (e.g., Met receptor, EGFR, and so on) and their downstream signalling such as PI-3 kinase has been reported in high-grade ovarian tumours." (PMID 18349831, 2008). "MMP-9 co-upregulation was also observed in our study, which is in agreement with the finding that MMP-9 (and MMP-14) mRNA levels are selectively increased in response to EGFR activity in ovarian tumor cells." (PMID 18211683, 2008). "Epidermal growth factor receptor (EGFR) was studied in ovarian tumours with immunohistochemical (IH) and ligand-binding assay (LBA)." (PMID 1457340, 1992). "We speculate that it would be beneficial for patients with EGFR+ ovarian tumors that secrete TNFα to consider a combination regime of anti-EGFR mAb, like cetuximab, and TNFα blocking agents." (PMID 33540543, 2021). "With respect to the primary ovarian tumors, EGFR, VEGF-A and L1CAM were heterogeneously expressed." (PMID 32545676, 2020).